BRAF (B-Raf proto-oncogene, serine/threonine kinase)
Diseases named in the same sentence as BRAF in open-access papers (continued):
Sharing a sentence is not in itself a finding about the gene and the disease.
melanoma (continued). "Interestingly, a study using a xenografted mice melanoma model has reported a vascular remodeling process which is mediated by the transduction signaling of the IGF1/IGF1R axis, contributing to the development of the melanoma cells which have acquired resistance to BRAF inhibition." (PMID 37174072, 2023). "Because expression of SOX-10 and BRAF V600E were negative in all cases, melanoma could be excluded." (PMID 37470853, 2023). "Since positive SLNB in thick melanomas automatically increases staging from IIB/IIC to IIIC, such patients may be treated with adjuvant systemic therapy, including newer drugs such as immune-checkpoint inhibitors and/or BRAF/MEK inhibitors, which have been shown to improve PFS and OS." (PMID 37892990, 2023). "However, differences in ex vivo inhibition by dabrafenib might reliably predict responders and non-responders to BRAF inhibitor therapy, as shown for melanoma." (PMID 37760447, 2023). "Moreover, patients with BRAF V600E/K–mutant melanoma who received a previous BRAFi with or without MEKi had lower objective response rates (28.4% vs. 44.2%), four-year PFS (15.2% vs. 27.8%), and OS (26.9% vs. 49.3%), compared with those who had not received earlier targeted therapy." (PMID 35565255, 2022). "Knockdown of STAG2 in melanoma cells did not apparently affect cell cycle progression, apoptosis, or growth of xenograft tumors in nude mice, but significantly decreased the sensitivities of melanoma cells to inhibition of BRAF and/or MEK in both culture cells and xenograft mouse models." (PMID 35388001, 2022). "Overall these data support the involvement of SEMA6A in fibroblasts-induced protection of melanoma cells from the anti-tumor activity of dual BRAF/MEK inhibition and indicate that SEMA6A might be a good candidate predictor of short-term benefit from dual BRAF/MEK blockade." (PMID 35440004, 2022). "Finally, the melanoma patients received BRAF inhibitor with or without MEK inhibitor." (PMID 35058553, 2022). "Also in patients with BRAF-mutant malignant melanoma, no advantage of the intermittent administration of trametinib with dabrafenib could be found." (PMID 35965494, 2022). "Besides anti-BRAF/MEK targeted therapies, the recent discovery that immune checkpoint inhibitors, targeting regulatory molecules on T lymphocytes (anti-CTLA4, anti-PD-1, and anti-PD-L1), are highly efficient in melanoma patients has revolutionized the treatment of metastatic melanoma." (PMID 35494017, 2022). "Personalized timing based on assessment of mutant BRAF or KRAS amplification levels by sampling cfDNA for example, may be required to better elicit MAPK hyperactivation to forestall drug resistance using an intermittent dosing strategy in lung and melanoma patients." (PMID 36418460, 2022). "Concerning SA there are very few studies about the role of this secretory pathway in BRAF melanomas and we believe that this route may induce resistance not only in tumor cells, but it can also reprogram other stromal cells present in the TME through the secretion of important pro-tumoral molecules." (PMID 35008395, 2022). "Preclinical and clinical data obtained in BRAFV600E melanoma models and patients indicated that simultaneous and vertical targeting of more than one node along the MAPK/ERK pathway, such as BRAF and MEK, could bypass the resistance to BRAF inhibitors and delay the onset of relapse." (PMID 35582524, 2022). "Cutaneous melanomas are classified into four subtypes: (i) mutation of the B-Raf proto-oncogene serine/threonine kinase (BRAFmut), (ii) mutation of the NRAS proto-oncogene GTPase (NRASmut), (iii) mutation of neurofibromin 1 (NF1mut), and (iv) none of the three, triple BRAF/NRAS/NF1 wild-type (WT)." (PMID 36428530, 2022). "However, it is still not clear whether melanoma with amplification of BRAF experiences iterative selective sweeps and, if so, what the underlying molecular basis of this process might be." (PMID 33801689, 2021).
melanoma (continued). "Therefore, the selective inhibition of BRAF in NRAS mutant melanomas is not an adequate approach, as it can induce the paradoxical activation of RAF proteins and the concomitant ablation of BRAF and CRAF, leading to the emergence of resistant cells showing the ARAF-dependent reactivation of ERK." (PMID 34831002, 2021). "In this retrospective single institutional study, we found stage III melanoma patients treated with LND and adjuvant RT whose tumor exhibited a BRAF mutation had significantly worse local–regional control compared to patients with BRAF negative (wild-type) tumors." (PMID 34537078, 2021). "This means that they would not be appropriate for treating RAS-mutant cancers, however they could potentially be a future replacement for type I1⁄2 RAFi for the treatment of BRAF mutant cancers such as most melanoma and hairy-cell leukaemia without paradoxically inducing tumour formation." (PMID 33367512, 2021). "Along the same line, Polκ was very recently shown to be upregulated in melanoma, lung, and breast cancer cells treated with an inhibitor of the BRAF oncogene, contributing to drug resistance, probably by a non-mutagenic fashion, which may probably be through regulation of the DDR." (PMID 33920223, 2021). "Due to the small sample size of paired BRAF inhibitor samples from the BRAF inhibitor clinical trial, we could only identify a trend toward a correlation between CD40+ melanoma and patient survival, which warrants future trials to validate the role of CD40+ melanoma cells in treatment responses." (PMID 34092233, 2021). "Notably, the efficacy of this combinatorial treatment in melanoma cells is not influenced by BRAF, NRAS or NF1 mutational status, opening the possibility of using these compounds to treat melanoma expressing high levels of SOX2 and GLI1 irrespectively to their mutational status." (PMID 33958721, 2021). "Finally, analyzing biopsies from BRAFV600E mutant melanoma patients (n = 4) who had progressed upon vemurafenib treatment, these authors found that PTPN11 phosphorylation at Y542 can serve as a biomarker to identify tumors with RTK-driven acquired resistance to BRAF inhibitors." (PMID 34065438, 2021). "However, no study demonstrates the definite effect of BRAF or MEK inhibitor in mucosal melanoma." (PMID 33585548, 2020). "However, not all melanoma patients benefit from BRAF/MEK inhibitors or immunotherapies." (PMID 33024276, 2020). "We investigated the IRAK-M DNA methylation profiles of patient samples and melanoma cell lines and found that reduced methylation within the promoter region of IRAK-M correlated with increased transcript levels, neither did they correlate with BRAF or NRAS mutation status, nor CDKN2A genotype." (PMID 32533049, 2020). "Elevated autophagy accompanying melanoma progression has been associated with loss of galectin-3, increased levels of sirtuin 1 (SIRT1), SIRT6, BNIP3, and long non-coding RNA ZNNT1, and enhanced activity of signaling pathways such as AKT, independent of the mutational status of BRAF." (PMID 32340261, 2020). "In fact, although BRAF mutations are typically associated with a negative prognostic role especially in, lung cancer, melanoma, thyroid, and CRC, their positive predictive role has recently emerged in melanoma, lung cancer, thyroid carcinoma, CRC, and other cancers, such as glioma patients." (PMID 33260892, 2020). "Thus, similar to BRAF mutant CRC, the efficacy of BRAF inhibitors in melanoma was limited by the relief of feedback inhibition of RTK-RAS-RAF with consequent MEK-ERK pathway reactivation, an effect that could be blocked with combined BRAF/MEK inhibition." (PMID 32922659, 2020). "On the contrary, melanomas with BRAF class-2 mutations (non-V600 mutations) do not respond to first-generation BRAF inhibitors, which are monomer selective, but they could be of benefit to MEK/ERK inhibitors as well as the BRAF inhibitor PLX8394." (PMID 32695793, 2020).
melanoma (continued). "Moreover, celecoxib reduced the negative response of melanoma cells to BRAF inhibitors." (PMID 32296574, 2020). "Ongoing work in this model, which does not carry mutations in the BRAF and PTEN genes frequently associated with melanoma, may be particularly relevant to understanding the progression of the still large percentage of melanomas not driven by mutations in these two genes." (PMID 32175283, 2020). "In addition, melanomas that do not carry the BRAF oncogenes cannot be subjected to this type of therapy and are limited to treatments with immune checkpoint inhibitors, such as nivolumab, or combination of nivolumab with ipilimumab, approved by the FDA in 2016." (PMID 31040916, 2019). "Although the response rate to BRAF inhibitor plus MEK inhibitor combination therapy is as high as 67%, median progression-free survival (PFS) is approximately 12 months, suggesting the need for additional promising methods that could prolong anti-melanoma effects." (PMID 31514399, 2019). "Finally, we show preliminary evidence that a combination of Breslow thickness, mitotic count and BRAF immunohistochemistry may identify a group within superficial spreading melanomas with an improved survival probability independent of SNB analysis." (PMID 31039200, 2019). "Indeed, BRAF has been incriminated in the MAPK pathway overstimulation, resulting in the downstream stabilization of the hypoxic inducible transcription factor-1alpha (HIF-1α) in BRAFV600E melanoma, a transcription factor also overexpressed in the BRAF-mutated MDA-MB-231 breast cancer cell lines." (PMID 31744229, 2019). "Even though both BRAF-mutant A375 and NRAS-mutant WM1366 cells responded similarly to CDK11 down-regulation with respect to loss of cell survival capability and accumulation of G1-phase cells, these 2 types of melanoma did not respond identically at the molecular level." (PMID 30987032, 2019). "Our melanoma-prone Grm1 transgenic mouse models (TG-3 and EPv) do not harbor a BRAFV600E mutation (unpublished data), which is consistent with our in vitro cultured cell studies, that introduction of exogenous Grm1 cDNA into melan-a cells (MASS clones) did not induce mutation of BRaf." (PMID 29464040, 2018). "However, melanoma cell proliferation was inhibited in these and other cell lines regardless of whether BRAF underwent degradation." (PMID 29481571, 2018). "Therefore, targeting the cGMP/PKG pathway could open a new therapeutic strategy for V600E BRAF negative melanoma where no effective treatment is available at the moment." (PMID 29435180, 2018). "In addition, we showed that inhibition of mutant B-Raf enhanced PMCA4b expression in BRAF mutant melanoma cells, and that PMCA4b abundance (induced either by overexpression or drug treatments) was coupled with decreased migration and metastatic activity of BRAF mutant melanoma cells." (PMID 30352569, 2018). "The results here suggest that the use of a combination of MCL-1 and BCL-2 inhibitors to induce NOXA and BIM is a promising treatment strategy for melanoma regardless of the mutation status of BRAF or NRAS, and it may overcome melanoma's resistance to current treatments." (PMID 27086916, 2017). "In contrast to the inhibition of proliferation of NB xenografts observed in the present study, BRAF V600E-mutated melanoma cells showed increased proliferation upon dietary intervention with an LCT-based KD (75% fat), whereas NRAS Q61K-mutated and wild-type melanoma cells were not affected." (PMID 29029389, 2017). "Moreover, Pak inhibitors and BRAF inhibitors did not synergistically kill melanoma cells, suggesting that the effect of PAK inhibitors on MAPK signaling may not be responsible for the observed apoptosis effect." (PMID 28753606, 2017).
melanoma (continued). "However, whether the minor role of the oncogenic PD-L1 expression in the BRAF.PTEN melanoma model applies to tumor PD-L1 expression upregulated by other tumor-intrinsic mechanisms in different types of cancer is unclear." (PMID 29255458, 2017). "Other potential mechanisms by which targeting BRAF might restore the immune system include the impairment of Tregs and MDSC activity and the down-modulation of the C-C chemokine ligand (CCL)-2 that is primarily involved in melanoma cell recruitment within the tumor milieu." (PMID 29285320, 2017). "Moreover, correlation between cMET expression and HGF rescue in vemurafenib-treated BRAF-mutant melanoma cells was not high in this study (r2 = 0.56) suggesting that cMET contribution to microenvironment-mediated BRAF-inhibitor resistance remains to be clarified." (PMID 28829835, 2017). "ADA also inhibited the proliferation of all the other human melanoma cell lines employed in this study, namely SK-Mel-5, SK-Mel-28, WM983A, and PES43 cell lines, all carrying the BRAFv600E mutation and the WM3060 cell line wild type for BRAF, without affecting NHEM proliferation." (PMID 28289382, 2017). "In this study, we observed that BRAF mutated A375 melanoma cells with LKB1 knockdown in vitro displayed a stronger migration and invasion ability than LKB1 intact A375 cells, while BRAF wild type MeWo melanoma cells with LKB1 knockdown did not enhanced invasion and migration ability." (PMID 29371951, 2017). "On the one hand, melanomas with chronic sun-induced damage (CSD) harbor mutations in KIT proto-oncogene receptor tyrosine kinase (KIT, Gene ID: 3815), NF1, NRAS, and BRAF but typically not BRAF(V600E), the specific BRAF mutation that commonly arises in atypical melanocytic neoplasms." (PMID 28265786, 2017). "Notably, Ets-1 is induced by BRAF or MEK kinase inhibition, resulting in increased NRAS expression, which could be blocked by inactivation of Usp9x and therapeutic combination of Usp9x and MEK inhibitor fully suppressed melanoma growth." (PMID 28198367, 2017). "Therefore, the assumption that BRAF but not CRAF could be dispensable for NRAS-induced melanoma appears paradoxical." (PMID 28497782, 2017). "Moreover, RTK signaling has been linked to an intrinsically BRAF inhibitor resistant phenotype, which was unexpected, as RTK signaling was not perceived as being a major driver of human melanoma." (PMID 27200346, 2016). "To test whether the same association could be observed in clinical samples, we investigated MHC-II/HLA-DR expression by IHC in a tissue microarray (TMA) of melanoma patient samples (n=67) with known BRAF and NRAS genotypes who largely had not received immune therapy." (PMID 26822383, 2016). "Moreover, the gene expression reciprocity between NF-κB and MITF in melanoma and a transition between phenotypes MITF-Mhigh/NF-κBlow and MITF-Mlow/NF-κBhigh as a part of melanoma plasticity in response to therapies targeting the BRAF/MEK/ERK pathway have been proposed." (PMID 26824319, 2016). "However, not all BRAF-V600E melanomas respond to MAPK inhibition." (PMID 27655717, 2016). "Furthermore, BIs are not effective against the ~40% of melanomas that express wild-type BRAF." (PMID 26808375, 2016). "Nivolumab was FDA-approved for the treatment of advanced melanoma in December 2014, following the publication of results from a completed Phase III clinical trial demonstrating a significant improvement in progression-free and overall survival in patients with melanoma without the BRAF mutation." (PMID 26343198, 2015). "Indeed, AXL+/WNT5A+ melanoma cells are resistant to MAPK pathway inhibitors and this might, at least in part, be due to the fact that the regulation of MITF expression is disconnected from BRAF." (PMID 25818589, 2015).
melanoma (continued). "These pan-negative melanomas did not harbor mutations in MEK1 or 2, nor did they display increased RAS activity, both of which are implicated in previous citings of paradoxical MEK1/2 activation upon MEK1/2 inhibition, specifically in the BRAF V600-mutant setting." (PMID 26084293, 2015). "Therefore, SCH772984 may be clinically applicable as a treatment for non-BRAF mutant melanoma or in BRAF-mutant melanoma with innate or acquired resistance, alone or in combination with BRAF inhibitors." (PMID 25142146, 2014). "In the current study, BRAF and NRAS mutational status was not identified as a prognostic marker in stage III melanoma patients with macroscopic nodal involvement, but had a neutral role in terms of patient survival, which may be of importance for potential adjuvant therapy." (PMID 24959217, 2014). "Importantly, these cells have no oncogenic RAS or BRAF mutations, and PLX4720 conferred no significant proliferative advantage to the tested cells even when used at concentrations that inhibit the proliferation of BRAFV600E melanoma cell lines." (PMID 24192036, 2013). "Melanoma‐EVs were shown to enhance cell migration and proliferation and reduce the effectiveness of BRAF inhibitors, though not MEK inhibitors or combined BRAF/MEK therapy." (PMID 40883983, 2025). "Although the baseline level of TAZ protein did not predict the response to BRAF inhibitors in a panel of BRAFV600E melanoma cell lines, ectopic overexpression increased resistance in several BRAFV600E melanoma cell lines." (PMID 39856157, 2025). "In line with PREX2 deficiency, this mutation had no impact upon disease trajectory, with naevus onset, melanoma initiation, and overall survival of BRAF PTEN PREX2-GD animals equivalent to the BRAF PTEN control cohort." (PMID 39636745, 2025). "Although the therapeutic landscape for advanced melanoma has radically changed in the last decade since the approval of the different ICI regimens and BRAF/MEKi, a significant percentage of patients still do not benefit from these therapies." (PMID 39273452, 2024). "In Saskatchewan, reflex BRAF-only testing is performed for all pT4 (>4 mm in thickness) melanomas, stage III and IV melanomas, and all melanomas with ulceration regardless of thickness." (PMID 39661469, 2024). "In these melanomas, MAPK is activated via CRAF, not BRAF, and these tumors also have aberrant cyclin-dependent kinase (CDK) 4/6 expression and hyperactivated PI3K/AKT signaling." (PMID 38732242, 2024). "Mass spectrometry‐-based chemical proteomics analysis of dabrafenib target profiles in melanoma cells identified a putative interaction with GCN2, a predicted property not shared by another BRAF inhibitor, vemurafenib." (PMID 38421883, 2024). "Unlike melanoma, BRAFV600E mCRC does not respond to BRAF inhibitor monotherapy, and it responds only poorly to conventional chemotherapy." (PMID 36759733, 2023). "Also, the co-occurrence of NRAS and BRAF, the two most frequently mutated genes in melanoma, is also rarely reported (2.9%), which is in agreement with our observations as we found concomitant NRAS/BRAF variants in 5 (1%) of our melanoma samples; however, their clinical impact is not known." (PMID 37483495, 2023). "Colorectal NECs have similar EGFR methylation signatures to melanoma, unlike CRC, and BRAF inhibitor monotherapy showed much higher tumor regression in colorectal NECs than CRC in patient-derived xenograft models." (PMID 37422534, 2023). "We also found patients with melanoma in our tissue and plasma cohorts who did not respond to dual ICI despite a positive BRAF-mutant status." (PMID 37525015, 2023). "In another study, the combined treatment of BRAF/MEK inhibitors vemurafenib and trametinib in melanoma xenografts showed no significant changes in lactate-to-pyruvate ratios before treatment and after 24 h of combination treatment." (PMID 37233647, 2023).